CD4 (CD4 molecule)
Diseases named in the same sentence as CD4 in open-access papers (continued):
Sharing a sentence is not in itself a finding about the gene and the disease.
tumor (continued). "Research indicates that Candida albicans can promote the activation and recruitment of CD4+ T cells and CD8+ T cells to tumor sites by modulating the CTLA‐4 signaling pathway." (PMID 41574027, 2026). "T cell exhaustion is a major barrier to effective tumor immunotherapy, with most mechanistic studies focusing on CD8+ T cells, while CD4+ T cell exhaustion is comparatively underexplored." (PMID 41484912, 2026). "CD40, a member of the tumor necrosis factor superfamily, induces growth arrest and apoptosis when overexpressed in tumor cells and activates dendritic cells to enhance CD4+ and CD8+ T cell anti-tumor effects." (PMID 41514678, 2026). "The panel allowed for identification of DCN, CD4+ T cells, CD8+ T cells, CD20+ B cells, CD68+ macrophages, and PanCK+ tumour cells." (PMID 41392017, 2026). "In contrast, the same 1:1 mixture of primary CD4+ and CD8+ T cells resulted in reduced exhaustion marker expression after repeated tumor challenge." (PMID 41484912, 2026). "This synergy was driven by tissue-resident memory T (TRM) cell enrichment in the tumor microenvironment (TME), which reached 15.2% in CD4+ T cells and 12.9% in CD8+ T cells." (PMID 41993212, 2026). "DCs, the most potent antigen-presenting cells (APCs), phagocytose tumor material, process antigens, and migrate to lymph nodes, where they present peptides via MHC class I and II molecules to naïve CD8+ and CD4+ T cells, respectively." (PMID 41601669, 2026). "The tumor necrosis factor (TNF) ligand, which is generated by stromal cells, tumor-associated macrophages, endothelial cells, and cancer cells, has anti-tumor effects and amplifies the action of CD8+ and CD4+ T cells, inducing apoptosis and inflammation." (PMID 41596472, 2026). "In their study, the proportions of TIGIT+CD3+, TIGIT+CD4+, and TIGIT+CD8+ T cells in the peripheral blood of CRC patients were higher than in healthy donors, and these subsets were even more enriched in tumor tissue than in matched blood samples." (PMID 41596586, 2026). "Specifically, ICCP NPs significantly enhance dendritic cell maturation (∼8-fold), increase CD4+ T cell infiltration (∼5.5-fold), and boost CD8+ T cell infiltration (∼6.5-fold), thereby reversing the immunosuppressive tumor microenvironment." (PMID 41800456, 2026). "CD4+, CD8+, and CD68+ cell densities at the tumor center and invasive front were quantified using multiplex immunofluorescence imaging." (PMID 41792411, 2026). "These included the objective response rate (ORR), improvement of TCM-related symptoms, levels of tumor markers CEA and CA199, immune function indicators (CD3+, CD4+, CD4+/CD8+, NK cells), and quality of life as measured by the KPS score." (PMID 41658566, 2026). "Adrenergic signaling through β2-adrenergic receptor (ADRB2) is a conserved neuro-immune axis that modulates tumor biology at multiple levels: tumor cells, stromal compartments (CAF, endothelium), myeloid populations (MDSC/TAM), and lymphocytes (CD4+/CD8+)." (PMID 42292793, 2026). "Flow cytometry demonstrated a marked reduction in tumor-infiltrating CD4+CD25+Foxp3+ regulatory T cells, indicating modulation of the tumor immune microenvironment." (PMID 42192889, 2026). "High-PBK tumors showed an immune-activated microenvironment, including increased CD4+, CD8+, and FOXP3+ T-cell infiltration, higher stromal PD-L1 expression, and higher tumor-infiltrating lymphocyte scores." (PMID 41681955, 2026). "Clec9A-targeted nanoparticles directing CD4 and CD8 neo-epitopes to cross-presenting dendritic cells (DCs) stimulate adjuvant-free therapeutically effective tumor-specific immunity." (PMID 42255099, 2026). "To further evaluate the immunosuppressive landscape within the tumor microenvironment, we analyzed FoxP3 and CD25 expression in CD4+ T cells." (PMID 41522339, 2026). "Tumor microenvironment and immune cell infiltration markers (CD3+, CD4+, CD8+, IFN-γ, granzyme B) were analyzed via flow cytometry and immunofluorescence." (PMID 41798950, 2026).
tumor (continued). "Dimensionality reduction and clustering identified distinct tumor‐infiltrating T‐cell subsets, including CD8+ Tex cells, CD4+ T cells, CD8+ T cells, Tregs, and γδ T cells." (PMID 41250935, 2026). "Cebpb overexpression promoted tumor growth in the immunocompetent syngeneic mouse models, which was accompanied by increased CTLA-4 expression in tumor-infiltrating CD4+ T cells." (PMID 41743630, 2026). "Our analysis reveals a dual role of T cell-macrophage crosstalk: CD4+ and CD8+ exhausted T cells drive anti-tumor M1-like TAMs activation via TNF-TNFRSF1A, TNFSF14-LTBR, and ICAM1-ITGAL/ITGB2." (PMID 42001468, 2026). "Flow cytometry analysis provided further evidence of immune activation, showing a marked increase in mature DCs in the spleen and a significant infiltration of CD3+CD4+ and CD3+CD8+ T lymphocytes in tumor tissues." (PMID 41424843, 2026). "Functionally, tumor control requires CXCL9-CXCR3 dependent CD4+ T cell recruitment, accumulation of stem-like memory CD4+ T cells, and germinal center like immune organization in tumor-draining lymph nodes." (PMID 41676642, 2026). "In agreement with our results, the immune triads formation among CD4+ T cells, CD8+ T cells, and DCs in tumor is reported to be critical for tumor elimination." (PMID 41348109, 2026). "The proportion of neutrophil/PMN‐MDSC was dramatically reduced in the tRF‐22 knockdown group, whereas anti‐tumor immune cells, including CD8+ T cells, CD4+ T cells, DC, and NK cells, increased." (PMID 41144758, 2026). "The reduced infiltration of CD4+ and CD8+ T cells into tumors further confirmed the effective blockade of tumor perfusion." (PMID 41900805, 2026). "Collectively, these data identify a subset of tumor-restraining, pro-immunogenic lymphocytes—CD8+GzmB+, CD4+IFN-γ+, CD103+ TRM, and CD69+ memory cells—whose activation predicts favorable outcomes and treatment responsiveness." (PMID 41562715, 2026). "Previous studies have identified the crucial role of TRIP13 in tumor immunity, where it supports tumor survival by modulating the recruitment of immune cells, including CD3+, CD4+, and CD8+ T cells, into the tumor microenvironment." (PMID 41535263, 2026). "In the tumor cells that were given UBS039, the PD-L1 and Sirt6 expression levels were also elevated, as was PD-1 expression in cocultured CD4 + T cells." (PMID 41530841, 2026). "Upon activation, CD4+ and CD8+ T cells migrate from the LNs into the TME, where they initiate anti-tumor immune responses." (PMID 41495426, 2026). "Lymphocytes are important components of the immune microenvironment, especially tumor-infiltrating lymphocytes, which are a mixture of CD8+ and CD4+ cells." (PMID 40416969, 2025). "In line with the observations in mice, the proportions of PD-1+, GITR+ and LAG-3+ cells increased among CD4+ and CD8+ T cells in the tumor compared to the blood." (PMID 39751916, 2025). "In the CRC data set, we analyzed co‐expression differences between CD4 and CD8 T cells in tumor tissue from 11 CRC patients." (PMID 40772737, 2025). "Along those lines, myeloid-specific KO of Gasdermin D (GSDMD) boosted anti-tumor immunity in anti-PD-L1-treated B16F10 melanoma-bearing mice, as characterized by elevated infiltration of CD4+ and CD8+ T cells, but also B cells and natural killer (NK) cells." (PMID 40098954, 2025). "In contrast, the cold (C2) tumour showed the enrichment of CD8+ naive T cells, CD4+ Th1 T cells, and B cell plasma." (PMID 41292185, 2025). "Sequential administration of the peptide vaccine and CPI induced CD4+ and CD8+ T-cell responses specific to multiple peptides, including peptides 3–5 and Survivin, correlating with tumor regression and durable remission." (PMID 41246310, 2025). "The downregulation of MHC class II expression on tumor cells after anti-PD-1 therapy in this study may contribute to resistance to anti-PD-1 therapy because it evades LAG-3 axis-mediated immunosuppression but inhibits activation of antitumor immune responses mediated by CD4-positive T cells." (PMID 40801643, 2025).
tumor (continued). "This resulted in the suppression of tumor progression and an increasing infiltration of CD8+ and CD4+ T cells in the tumor tissue." (PMID 40725148, 2025). "Anti-PD-1 predominantly leads to the proliferation of exhausted-like CD8+ T cells within the tumor, whereas CTLA-4 inhibitor mainly results in the amplification of CD4+ effector cells and exhausted-like CD8+ T cells." (PMID 40861801, 2025). "Tumor fragment 5 stood out as the most “immune-hot” region, with elevated expression of B2M, HLA-I/II, TAP1/2, and markers of CD8/CD4 T cell infiltration, which in turn correlated with its high antigen abundances." (PMID 40777321, 2025). "Antitumor immune responses require CD4+ TH1 cells to mediate the cytotoxicity of CD8+ T effector cells and to generate tumor-specific T cell memory." (PMID 41373645, 2025). "We also identified new potential trogocytic markers such as CD4 and CD53 on the trogocytic tumor samples." (PMID 40440354, 2025). "Monocle3 trajectories initiated from CD4 TN indicated a path TN → TCM → TEM → Treg, with normal-region cells at early pseudotime and tumor-core cells at terminal states." (PMID 41374989, 2025). "The PPMAD plus laser group exhibited a substantial elevation in CD3+CD4+ and CD3+CD8+ expression levels within the tumor, with the other groups also displaying varying degrees of improvement compared to the PBS group." (PMID 40110052, 2025). "Our findings are similar to a recent study defining immune triads that contain tumor-specific cytotoxic CD8+ T cells, CD4+ T cells, and antigen-presenting dendritic cells required to license tumor specific CD8+ T cells to eliminate cancer." (PMID 40475776, 2025). "Vaccines based on bacterial vectors present antigens carried by APCs and are recognized by T cells, which activate CD4+ and CD8+ T cells, thereby enhancing the immune response and inducing apoptosis of tumor cells." (PMID 40733649, 2025). "CD4 T cells enhance the antitumor activity of CD8 T cells and macrophages, consequently inhibiting tumor growth." (PMID 40274875, 2025). "Comparative gene expression analysis between tumour and paracancerous tissues showed that CD8+ T cells had more differentially expressed genes than CD4+ T cells." (PMID 40770837, 2025). "Tumor-derived miR-214 is transported to CD4+ T cells, where it promotes Treg expansion by downregulating expression of the PTEN tumor suppressor." (PMID 40647470, 2025). "Given the central role of CD4+ and CD8+ T cells in anti-tumor immunity and their predominance in our dataset, we focused our analysis on these subsets." (PMID 40475762, 2025). "For example, SNORA38B promotes IL-10 secretion in tumor cells, leading to the recruitment of CD4+FOXP3+regulatory T cells and reduced infiltration of CD3+CD8+T cells in the TME of non-small cell lung cancer (NSCLC), thereby promoting tumor progression." (PMID 41019058, 2025). "Flow cytometry analysis revealed a significantly enhanced activation of both CD4+ and CD8+ T cells in tumor tissues from the combination therapy group and the MMW treatment group." (PMID 41383334, 2025). "These inhibitors improve the CD8+ cytotoxic T cell to regulatory T cell (CD4+FOXP3+) ratio, modulate cytokine levels (including IL-4, IFN-γ, and TNF-α), and enhance the tumor immune microenvironment." (PMID 40573881, 2025). "T cells are lymphocytes that develop into many subsets, including CD4+ and CD8+ T cells, and are critical for the anti-tumor response." (PMID 39744577, 2025). "The analysis revealed that MZF1 expression was significantly positively correlated with B cells, CAF cells, endothelial cells, eosinophils, CD4+ T cells, NKT cells, CD8+ T cells, mast cells, monocytes, and Tregs cells in most TCGA tumor types." (PMID 40655141, 2025). "Human tumors can suppress immune cell activity, particularly that of anti-tumor effector cells such as CD8+ and CD4+ T lymphocytes, NK cells, and dendritic cells." (PMID 40407494, 2025).
tumor (continued). "Our investigation into the tumor microenvironment highlights the complex roles of macrophages (CD68+) and T-cells (CD4+, CD8+)." (PMID 40599139, 2025). "CD8+T cells were considered extremely important in anti-tumor immunity, which have been reported to be responsible for tumor cells elimination while CD8+T cells function was regulated by myeloid cells and CD4+T cells." (PMID 40535013, 2025). "During the first anti-tumor CD8+ T cell activation phase, CD4+ T cells inside tdLNs “license” APCs for efficient cytotoxic lymphocyte priming and maintenance as memory cells." (PMID 41030446, 2025). "We demonstrate a mechanism of macrophage-driven immune suppression in the tumor environment post-RT via CD80 and CD86-mediated expansion of CD4 T cells and Treg." (PMID 41417245, 2025). "HQ-30 targets cathepsin B (CTSB) to mediate PD-L1 degradation, which leads to increased infiltration of CD4+ T cells and CD8+ T cells in tumors, thereby reshaping the tumor microenvironment." (PMID 40006729, 2025). "In vivo, CuB reduced tumor growth and metastasis, enhanced CD8+ and CD4+ T cell infiltration, and reduced regulatory T cells (Tregs) and myeloid-derived suppressor cells (MDSCs)." (PMID 40896699, 2025). "Dual and triple immunotherapies induced changes in the tumor immune microenvironment compared to monotherapy, increasing the number of CD8+ T cells, CD4+ T cells, NK cells, and CD8+ /Treg ratio, while reducing Treg cells at the endpoint." (PMID 40796887, 2025). "GSE and AA enhanced tumor immune microenvironment through increasing CD8+ and CD4+ T cells accompanied by decreasing FOXP3+ Treg cells infiltrated in tumors." (PMID 40843004, 2025). "To investigate the interactions between CD4+ and CD8+ T cells, we first assessed the changes of CD4+ and CD8+ T cells in a B16F10 tumor model early after CTT (day 7), during the priming phase of CTT-induced Th1-dominant differentiation." (PMID 40277945, 2025). "Collectively, these findings clearly demonstrate that the apCAFs in the HNSCC regulate the CD4+/CD8+ T cell ratio, thereby promoting tumor growth." (PMID 39891284, 2025). "The tumor weights were significantly higher in the NKG2D blockade group and significantly lower in the CD4+ T cell depletion group compared to the control group." (PMID 40243581, 2025). "We performed immunohistochemical examination of CD4, CD8, CD68, and CD163 subpopulations in tumor sections." (PMID 41256864, 2025). "In the PDX model, although cmExoaCD11b has considerable therapeutic effect, we found that the expression of some immune cells, such as CD4+ T cells, CD8+ T cells, etc., was low in tumor tissues." (PMID 40548883, 2025). "In Oropharyngeal Squamous Cell Carcinoma (OPSCC) patients, the majority of TILs within the tumor are T CD8+ cells, although T CD4+ cells predominate in some patients." (PMID 40136652, 2025). "CXCL9, -10, -11 are CXCR3 ligands, expressed by several different cells within a tumor, that recruit T-cells and NK cells, with CXCL9 and 10 primarily recruiting activated CD4+ and CD8+ effector cells and CXCL11 recruiting or promoting development of T-regs." (PMID 40176808, 2025). "Immunofluorescence staining further corroborated the dramatic influx of CD4+ T, CD8+ T and Tregs cells into the tumor tissue." (PMID 39827246, 2025). "The Th1 subtype of CD4+ T cells (Th cells) can produce interferon gamma (IFNγ) and TNF-α to directly kill cancer cells and can exert anti-tumor effects by aiding B cells and CD8+ cells." (PMID 41001032, 2025). "When camouflage fails, tumor cells suppress immune effectors (DCs, NK cells, TH1 - polarized CD4+ T cells, CD8+ CTLs) and boost immunosuppressive cells (CD4+ CD25+ FOXP3+ Treg cells, specific TAM subsets, MDSCs)." (PMID 40661781, 2025). "Our findings reveal that lidocaine modulated the anti-tumor effects by decreasing IL-10, TGF-β, and IL-35 levels in CD4+CD25+Foxp3+TIICs, decreasing PD-1, and increasing IFN-γ expression in cytotoxic CD8+TIICs through the NF-kb pathway." (PMID 40244064, 2025).
tumor (continued). "Within tumor tissues, there was a high enrichment of CD4 Treg, CD8-Tem-PDCD1, CD8-Temra, and CD4 + Tex cells." (PMID 39354287, 2025). "The levels of CD4+ and CD8+ tumor‐infiltrating lymphocytes, as well as CD8+ T cell effector molecules IFNγ and GZMB, within the TME also dramatically increased in tumor‐bearing mice with dual‐drug therapy treatment." (PMID 40344511, 2025). "Further, CD4+ TTM dominated in ascites and tumor tissues with 53.64 ± 10.37% and 46.63 ± 8.79% of CD4+ T cells, respectively." (PMID 41221283, 2025). "Compared with αPD-1 and No-FMT treatment, the combination of αPD-1 and Re-FMT significantly inhibited the recruitment of CD4+ T cells (especially Tregs) and enhanced the recruitment of CD8+ T cells, B cells, and neutrophils in the subcutaneous tumor model." (PMID 40191185, 2025). "applied 10X Visium on 4 TNBC samples, showing that KLF5 expression co‐localised with basal markers (KRT5, KRT14, KRT17) in tumour regions, while areas with reduced KLF5 expression were enriched with CD4+ and CD8+ T cells." (PMID 40677104, 2025). "IHC results indicated a significant increase in the percentage of CD4+T cells, CD8+T cells, and CD19+B cells in the tumor sections of 10 μM CBD-treated mice as compared to the vehicle counterparts." (PMID 40475776, 2025). "Several studies have shown that high densities of tumor-infiltrating lymphocytes (TILs)—such as CD3+TILs, CD4+TILs, CD8+TILs and CD20+TILs – are favorable prognostic biomarkers." (PMID 41184299, 2025). "Immune profiling demonstrated reduced infiltration of CD4+ and CD8+ T cells, along with increased macrophage levels in the IMPC tumor microenvironment (TME)." (PMID 40821778, 2025). "There is a growing evidence indicating that reducing Treg cells leads to a rise in the amount of CD4+ and/or CD8+ effector T cells (Teffs) within tumors, enhancing the body's ability to fight against tumors and resulting in tumor rejection." (PMID 40224950, 2025). "Concurrently, this study validated the high expression of CLDN18.2 in a large clinical cohort, emphasizing its crucial value in early tumor prognosis assessment and its interaction with immune‐related molecules, such as PD‐L1, CD3, and CD4." (PMID 40019387, 2025). "further showed that the density of CD4+T cells in the tumor microenvironment of patients in the low PNI group, was significantly reduced, and CD4+T cells exert anti-tumor effects by activating CD8+T cells." (PMID 40896424, 2025). "Consistently, our recent study revealed that immunizations with nonreplicable MC38 CRC cells plus rGRA6Nt adjuvant potently activate not only CD8+ cytotoxic T cells but also IFN-γ production of both CD4+ and CD8+ T cells specifically to the tumor cells." (PMID 40832663, 2025). "This dual CD4+ and CD8+ T cell response supports not only the anti-tumor potential of CD8+ T cells, but also the CD4+ T cell support of CD8+ T cell activation and direct cytotoxic activity." (PMID 40227779, 2025). "Their subsets, CD4 + and CD8+, participate in immune responses and exert cytotoxic effects in eliminating tumor cells." (PMID 41040673, 2025). "Flow cytometric analysis of tumor-infiltrating lymphocytes indicated a reduction in the number of infiltrating CD3, CD8, and CD4 T lymphocytes in the MEKi+RT+anti-CXCR3 group compared to the MEKi+RT+isotype group." (PMID 41368644, 2025). "Conventional T cells are converted to CD4 + CD25highFoxP3+ Treg cells in a way that is reliant on TGFβ1 and IL10 since neutralizing antibodies specific to TGFβ1 and/or IL10 prevents tumor-derived EVs from proliferating Treg cells." (PMID 40407494, 2025). "Anti‐CD4 and anti‐CD8 neutralizing antibodies were administered to evaluate how CD4+ T or CD8+ T influenced the tumor‐promoting effects of Plac1 expression." (PMID 40056047, 2025).